GATA3 (GATA binding protein 3)
Diseases named in the same sentence as GATA3 in open-access papers (continued):
Sharing a sentence is not in itself a finding about the gene and the disease.
tumor (continued). "GATA3 could activate downstream miRNA-29b and prevent the synthesis of proteins required for tumor metastasis." (PMID 32760217, 2020). "Moreover, our explorations into TCGA database further suggest the relevance of GATA3 expression to the tumor size, distant metastasis, and pathologic stage in ccRCC patients." (PMID 31636361, 2020). "Moreover, by analyzing Treg cells derived from different donors in spleen chimera mice (lung metastasis model), we further confirmed the enhanced expression of Tbet and GATA3 in KO Treg cells compared with WT ones in both tumor tissue and dLNs." (PMID 32477338, 2020). "The axis of GATA3/FMNL1/CXCR2 may present a promising therapeutic target for tumor metastasis in ccRCC." (PMID 33324547, 2020). "However, from in vitro experiments, knockdown or overexpression of GATA3 did not significantly affect cancer cell apoptosis, but down-regulation of GATA3 promoted tumor growth and increased Oxa resistance of the CRC cells." (PMID 32760217, 2020). "3.3, we show the nodes having high role A and B motif centrality, such as HIFs, HDAC, BRCA1, EGR1, STAT1, GATA1 and GATA3, and also report their functions as master regulators in liver function, cell proliferation, tumor suppression and genomic stability, etc. as well as stress response." (PMID 32541819, 2020). "And tumor infiltrating Bcl6–/– Treg cells exhibited markedly decreased expression of Foxp3, while upregulating the expression of TFs and cytokines related to other lineages, including Tbet, RORγt, GATA3, IL4, and IL17, suggesting a weakened lineage stability." (PMID 32477338, 2020). "Although GATA3 could up-regulate miR-29b expression, the tumor-suppressive effect of GATA3 was partially reversed by miR-29b antagomir." (PMID 32760217, 2020). "Second, ER and GATA3 are closely related in the hormonal pathway, but they could still have distinct functions as to tumor progression." (PMID 31718619, 2019). "The notion that BMP4 enforces tumor dormancy is supported by its ability to block in-vitro tumor sphere formation, to diminish the expression of Nanog, Sox2, and Taz, and increase that of GATA3." (PMID 31547567, 2019). "While identifying novel associations, which to our knowledge have not been previously reported such as the linkage between nucleosome gene expression and GATA3 mutation type in BRCA, the analysis recovers many associations that are coherent with known tumor biology." (PMID 30993001, 2019). "Interestingly, consistent with results from in vitro experiment, GATA3 expression increased along with re-expression of ERα in 4T1 tumor tissues after GSK343 treatment for 9 days." (PMID 31704972, 2019). "However, because of the interpretation difficulty of GATA3 based on the extremely low proportion of positive tumor cells, the application of p63 IHC is more highly recommended since it is easily recognizable even in small biopsy materials." (PMID 31831043, 2019). "The 4 IHC markers defining the BASQ subtype of MIBC, CK14-positive, CK5/6-positive, GATA3-negative, FOXA1-negative expression were not readily applicable to non-muscle-invasive papillary UTUC because positivity for CK14 and negativity for GATA3 or for FOXA1 was rarely observed in this tumor." (PMID 30699951, 2019). "Interestingly, GATA3 as a repressor of pro-inflammatory, T-bet dependent effector differentiation is involved in the dysfunction of tumor infiltrating CD8+ T cells." (PMID 31396219, 2019). "Moreover, GATA3 was found to promote the expression of microRNA-29b (miR-29b), which in turn induces differentiation, suppresses metastasis and changes the tumour microenvironment." (PMID 30463912, 2018). "The GATA3-mutant cells became more aggressive and exhibited faster tumor growth in vivo." (PMID 29535312, 2018).
tumor (continued). "Moreover, results of tumour xenograft models showed that GATA3 overexpression in OEC-M1 cells significantly enhanced tumour growth in vivo." (PMID 28263977, 2017). "These genes, which could be transcriptional targets of GATA3, may work cooperatively with those in the HIF-1 pathway, and partly contribute to the GATA3-mediated tumour malignancy under hypoxia." (PMID 28263977, 2017). "The role of GATA3 in tumour malignancy varies in different cancers." (PMID 28263977, 2017). "In another study, increased regulatory T cells and tumor-associated macrophages in the tumor microenvironment were also associated with non-responsiveness, while increased GATA3+ and CD4+ T cells were associated with responders." (PMID 28974949, 2017). "We thus extended our study to evaluate GATA3 expression in 151 HNSCC tumours." (PMID 28263977, 2017). "This fact may support the hypothesis of an inverse correlation of GATA3 and T-bet expression, suggesting that the presence of Th2 immune cells limits functional Th1-type responses within the tumor microenvironment." (PMID 28005163, 2017). "GATA3 mutation enhanced tumor growth in vivo but did not affect sensitivity to clinically used hormonal therapies or chemotherapeutic agents." (PMID 29262572, 2017). "Results showed that GATA3 was highly expressed in 31% (47/151) of the HNSCC tumours." (PMID 28263977, 2017). "We also demonstrate that GATA3 may be an important protein involved in the functions of miR-155 in tumor progression." (PMID 28599307, 2017). "Altogether these results indicate that GATA3 might be playing a dual role in the regulation of FOXP3 transcription in tumor-CD8+ Treg cells." (PMID 28487507, 2017). "Transcriptional profiling classified the Ta tumours as luminal (high expression of luminal markers such as GATA3, PPARG, FOXA1 and XBP1 as well as differentiation markers such as UPK1A and KRT20) as well as non-aggressive (high expression of SKAP2, FABP4, MBNL2 and ID1)." (PMID 28916750, 2017). "Therefore, to understand the thorough function of GATA3 during the entire process of tumour progression, it will be of great interest to identify the transcriptional targets of GATA3 under normoxia." (PMID 28263977, 2017). "Our findings suggest that GATA3 may be involved in multiple tumor-related pathways (e.g., STAT/JAK pathway) in B-ALL to impact leukemogenesis through epigenetic regulation." (PMID 28415601, 2017). "To evaluate whether there is correlation between GATA3 and tumour cell proliferation in clinical samples, we performed IHC of Ki-67 in tumours from patients operated from year 2013 to 2014 (n=56)." (PMID 28263977, 2017). "Among the 151 tumours, 49 tumours were positive for both GATA3 and HIF-1α staining." (PMID 28263977, 2017). "These truncated proteins (hereafter referred to as GATA3-trunc) are stable and expressed in tumours, and, as GATA3 likely forms a homodimer, it is probable that they may act in a dominant negative manner." (PMID 27588951, 2016). "However, the tumor suppressor activity of GATA3 has been challenged by recent reports showing that GATA3 is similarly expressed in both primary and metastatic breast carcinoma." (PMID 27556500, 2016). "Third, high GATA3 expression may directly up-regulate VEGFα secretion by tumor cells, thus promoting neovascularization in the tumor microenvironment and increasing the malignant behavior and metastatic ability of cancer cells." (PMID 27589565, 2016). "This indicates that genes like BCAS1 are differentially expressed in tumours that contain the GATA3-ext mutation but not in tumours harbouring the GATA3-trunc mutation." (PMID 27588951, 2016). "To investigate whether the tumours with high immune gene expression (as represented by CD8A expression) show low levels of GATA3, ESR1 and PGR, we scattered each of these proteins against CD8A RNAseq counts." (PMID 26729235, 2016).
tumor (continued). "Our MCF10A cell line model does not fully recapitulate the context of GATA3 mutations in tumours in several ways, among them the heterozygous mutation state and the ER status." (PMID 27588951, 2016). "Differential gene expression in GATA3-ext tumours may indicate distinct tumour characteristics and this could affect disease progression and therapeutic response." (PMID 27588951, 2016). "This implies that these genes are differentially expressed in GATA3-ext tumours." (PMID 27588951, 2016). "To pinpoint whether GATA3 was involved in the inhibitive effect of miR-720 on tumour cell migration, we ectopically expressed GATA3 in miR-720 overexpressed THP-1 cells." (PMID 27354564, 2016). "For example, miR-29, a miRNA regulated by GATA3, inhibits metastasis by targeting a network of pro-metastatic regulators involved in angiogenesis, collagen remodeling and proteolysis, suggesting that a miRNA can function by altering the tumor microenvironment." (PMID 26044957, 2015). "Interestingly, GATA binding protein 3 (GATA3) was the protein most frequently associated with death in our analysis, and GATA3 expression was significantly decreased in tumor samples from stage I-II deceased patients." (PMID 26097693, 2015). "Furthermore luminal tumours express high levels of GATA3 and ER similar to luminal breast cancers and basal like tumours display enhanced MYC and E2F3 pathway signatures." (PMID 26316886, 2015). "For GATA3, we predicted that the SNP risk allele would not show tumor PAI in HeH ALL subjects, and this was the case (p = 0.5)." (PMID 26575185, 2015). "Gata3 plays a key role in airway remodeling during organ development and this transcription factor functions as a tumor suppressor by controlling the expression of lung metastasis inhibitors (DLC1 (deleted in liver cancer 1) and PAEP (progestagen-associated endometrial protein)." (PMID 26427040, 2015). "Furthermore FOXA1 and GATA3 are frequently downregulated in basal tumour but rarely over-expressed or amplified in luminal cancer while PBX1 is among the top upregulated genes and is frequently amplified in luminal cancers." (PMID 26215677, 2015). "Amongst the tumor specific genes Gata3 was of great importance." (PMID 26427040, 2015). "Univariate analysis showed that age (P = 0.041), tumor size (P<0.001), lymphatic/venous invasion (P<0.001), GATA3 expression (P<0.001), depth of tumor infiltration (P<0.001), lymph node metastasis (P<0.001), and distant metastasis (P<0.001) were significantly related to overall survival." (PMID 24504018, 2014). "GATA3 levels were elevated in both the early neoplasias and cancers in this study and were highly correlated with ER and FOXA1 expression, but mutation status in these samples is unknown." (PMID 24887547, 2014). "We predict that mutations in GATA3 with similar characteristics to the mutation in MCF7 likely confer a growth advantage, particularly in pre-menopausal women, and are likely to occur early in tumor evolution." (PMID 24758297, 2014). "In BLBC, other GATA3-controlled cellular pathways, or lack of downstream ER signaling, may compensate for upregulation of BCL2, THSD4 and DACH1 by GATA3, resulting in a tumor suppressor function." (PMID 25410484, 2014). "We then addressed the effect of GATA3 overexpression in in vivo tumor growth." (PMID 25479686, 2014). "Taken together, these studies highlight the role of GATA3 as a tumor suppressor." (PMID 25479686, 2014). "Meanwhile, GATA3 has been demonstrated as a tumor suppressor gene of breast tumor." (PMID 24498120, 2014). "Finally, we showed that downregulation of GATA3 is required for progestin stimulation of both in vitro cell proliferation and in vivo tumor growth." (PMID 25479686, 2014). "Comparing normal and tumor renal tissues, decreased GATA3 protein and mRNA expression levels have already been observed, supporting the hypothesis that GATA3 may be epigenetically silenced in RCC." (PMID 24549248, 2014).
tumor (continued). "It has been reported that Gfi1b down-regulates Gata3 expression in tumor cells." (PMID 24098325, 2013). "Furthermore, analysis of TILs in tumor samples from the same patients showed that, in agreement with the data in the blood, the number of lymphoid cells expressing GATA-3 was significantly superior to that of lymphoid cells expressing T-bet." (PMID 23950747, 2013). "Although relatively few cases with a luminal primary tumor phenotype were GATA3(-), which precluded reaching statistical significance, these cases also tended to present worse distant metastasis-free survival than GATA3(+) cases, in agreement with previous work." (PMID 24205108, 2013). "The transcription factor GATA3 showed high levels of expression in ER+ tumor group." (PMID 23599813, 2013). "The characterization of TILs polarization in PDAC was initially reported in, in which the presence of Th2, Th1 and Tregs cells in tumor samples was evaluated by immunohistochemistry using specific antibodies for GATA-3 (i.e., to detect Th2 cells), T-bet (i.e., to detect Th1 cells) and FoxP3." (PMID 23950747, 2013). "As compared with the Luminal tumor defining gene signature, we observed that more genes from the c-Myb gene list overlapped this cluster than other luminal tumor transcription factor-defining gene lists (GATA3 and ER)." (PMID 20949095, 2010). "In agreement with the Th2 skew observed in circulating CEA specific CD4+ T cells, immunohistochemical analysis of tumor infiltrating lymphocytes showed a significantly higher number of GATA-3+ (Th2) compared to T-bet+ (Th1) lymphoid cells, supporting a Th2 skew also at the tumor site." (PMID 19798410, 2009). "It is not thus surprising that the transcription factor Tbx3, being involved in tumour progression, could control the GATA3 transcription factor." (PMID 19828084, 2009). "In line with the Kaplan–Meier curves, GATA-3 negativity does not account for an increased risk of recurrence in ERα-negative tumours." (PMID 19549328, 2009). "This is consistent with the requirement of GATA3 in differentiated tumours." (PMID 18533032, 2008). "Consistent with this, basal-like tumours have the lowest GATA3 expression and the worst prognosis." (PMID 18533032, 2008). "Nonetheless, we observed strong correlations between ER and many genes that have previously been shown to be strongly associated with ER positivity, including GATA3, FOXA1, AGR2, AR, and STC2, in microarray profiling studies of mixed ER-positive and ER-negative tumours." (PMID 17555561, 2007). "The functional role of GATA3 in the tumor immune microenvironment also remains unclear." (PMID 40856420, 2025). "In GATA3-deficient mouse models, tumors were poorly differentiated and exhibited enhanced EMT and metastatic potential, demonstrating that BRCA1-mediated regulation of GATA3 is essential for maintaining epithelial differentiation and restraining tumor dissemination." (PMID 41514651, 2025). "Interestingly, the stability of GATA-3 in the brain may suggest site-specific differences in the immune microenvironment or tumor-immune interactions." (PMID 40283008, 2025). "Moreover, the BC subtype transcriptome analysis indicates that the original donor BC tumor tissue expresses only a few genes related to the luminal/smooth muscle subtype (GATA3/DES), while the PDX cell line differentiated into a basal subtype (KRT5/6A and COL17A1)." (PMID 40801146, 2025). "In PCMC, the diffuse and strong positivity of GATA3 (e.g., 90% tumor cell positivity in this case) not only provides critical support for the hypothesized apocrine origin but also underscores its potential dominant role in the tumor’s molecular regulatory network." (PMID 40969274, 2025). "Together with our previous finding that depletion of Gata3 in these luminal tumor cells promotes basal-like differentiation in tumors newly generated, these data demonstrate that depletion of Gata3 in luminal tumor cells also impairs DNA damage repair and promotes basal-like differentiation." (PMID 38627785, 2024).
tumor (continued). "Furthermore, there was a rise in the quantity of Th2/GATA3 expression in the lung metastasis tissues of mice injected with the 4T1Cct6a group compared to 4T1EV, showing a decline in the tumours of the 4T1Cct6a+Trim21 mice group compared to the 4T1Cct6a+Trim21‐ΔRING mouse group." (PMID 39556022, 2024). "However, reconstitution of c-Fos fails to restore epithelial features in Gata3 deficient tumor cells." (PMID 37353480, 2023). "Transcription factor GATA3, which can bind to the C8orf76 gene promoter, is expressed at an early stage of thymus development and participate in thymocyte differentiation as well as in control lymphoid cell differentiation, being a tumor suppressor in B-cell lymphomagenesis." (PMID 37373333, 2023). "Furthermore, depletion of Gata3 in luminal tumor cells activates EMT." (PMID 37353480, 2023). "Thus, ST2 was used as a surface marker to isolate GATA3+ Tregs in tumor-draining LNs." (PMID 36107619, 2022). "Additionally, the tumor was positive for estrogen receptor (ER) and progesterone receptor (PR), suggesting that it was likely derived from the mammary gland; this was supported by GATA-binding protein 3 (GATA3)-positive staining." (PMID 36528621, 2022). "Immunohistochemistry for GATA-3 may indicate that the tumor originated from the breast." (PMID 36254025, 2022). "Interestingly we found that CDKN2A,FADD,GATA3,MYC were highly variable between gain and loss in CNV, while at the mRNA expression level these same NRGS were also found to be significantly different in normal tissues compared to tumor tissues." (PMID 35478725, 2022). "Furthermore, AC092580.4 expression is strongly correlated with key immune genes and pathways including Gata3 expression, suggesting that it may be involved in modulating T cell polarization and hence anti-tumor immunity." (PMID 36180904, 2022). "Therefore, specific repression of KLHL42 by GATA3 might be one of the critical routes for 5-FU preventing tumor progression in CTCL." (PMID 36400759, 2022). "Overall, E2 levels were significantly positively correlated with tumor enrichment in the hallmark estrogen response pathway (red bars) and with the expression of genes demonstrated to be transcriptionally regulated by ER (BCL2, IGF1R, GATA3, PIK3CA) and ligand-dependent ER (ESR1, XBP1, TFF1)." (PMID 36428742, 2022). "Scientists explored the possible association between the presence of c-MYC, GATA3, and a high level of Ki-67 expression in PTCL patients to confirm whether the GATA3-positive subgroup of tumours is enriched in MYC and proliferative gene signatures compared with other groups." (PMID 35681778, 2022). "Due to growth and differentiation defects induced by Brca1 and Gata3 deficiency 15, 19, 29-32, mice deficient for either Brca1 or Gata3 rarely develop tumors, making it difficult to identify the role of Brca1 and Gata3 loss in regulating EMT in tumor development and metastasis." (PMID 34373738, 2021). "However, after neoadjuvant treatment the tumour lost expression of GATA-3." (PMID 33727576, 2021). "Indeed, GATA3 expression by cytotoxic T lymphocytes has been described as a mechanism of T cell exhaustion, particularly in autoimmune conditions, as well as a mechanism of tumour escape from the immune surveillance." (PMID 32575504, 2020). "The findings that GATA3 physically interacts with the UTX/MLL4 complex suggest that the tumor suppressive role of this complex might be ensured through the maintenance of a proper transcriptional-network activation by eliminating PRC2-induced putative oncogenic silencing." (PMID 31685800, 2019). "As FOXA1 is one of the early events in the ER pathway activation cascade, it might be possible that the oncogenic nature of ER pathway activation is already established in early neoplasia and continues to IDC as FOXA1 and GATA3 are frequently mutated in ER+/luminal breast tumors." (PMID 29720211, 2018).